NQO1 (NAD(P)H quinone dehydrogenase 1)
Diseases named in the same sentence as NQO1 in open-access papers (continued):
Sharing a sentence is not in itself a finding about the gene and the disease.
prostate tumors (3 papers, 2010 to 2023). "Similarly, the expression of Nrf2 as well as its downstream target genes such as UGT1A1, GSTM1 and NQO1 were found to be gradually down-regulated in prostate tumors with the progression of prostate tumorigenesis in TRAMP mice." (PMID 20062804, 2010). "Importantly, our biological data provide mechanistic details for the reported correlation between decreased NQO1 transcript and poorly differentiated metastatic prostate tumors and confirms our hypothesis that attenuation of NQO1 plays a role in TGFβ signaling mediated cancer cell plasticity." (PMID 31909204, 2020). "Recent studies from our laboratory and others have found that the expression levels of SOD, UGT1A1, NQO1 and several GST family genes were significantly suppressed in prostate tumors in Transgenic Adenocarcinoma of Mouse Prostate (TRAMP) mice." (PMID 20062804, 2010).
sarcoma (3 papers, 2015 to 2025). A usually aggressive malignant neoplasm of the soft tissue or bone. "Conversely, the NQO1 mRNA expression was lower in males with kidney renal papillary cell carcinoma and sarcoma." (PMID 37583897, 2023). "Moreover, several instances of substantially diminished NQO1 levels in human sarcoma samples were also observed." (PMID 27625902, 2015).
small cell lung carcinoma (3 papers, 2015 to 2017). Small cell lung cancer (SCLC) is a highly aggressive malignant neoplasm, accounting for 10-15% of lung cancer cases, characterized byrapid growth, and early metastasis. "The NQO1 C609T polymorphism might result in failure of NQO1 protein to detoxify highly toxic quinones, and thus have some consequences for smoking-related small cell lung cancer risk." (PMID 29254245, 2017).
stomach cancer (3 papers, 2020 to 2023). "Furthermore, the Oncomine database, including Chen Gastric and Cho Gastric datasets, was also used to test the NQO1 expression difference between gastric tumor tissues and gastric normal tissues." (PMID 37188198, 2023).
vitiligo (3 papers, 2013 to 2020). Generalized well circumscribed patches of leukoderma that are generally distributed over symmetric body locations and is due to autoimmune destruction of melanocytes. "In melanocytes isolated from vitiligo patients we observed chronic activation of Nrf2, manganese superoxide dismutase 2 (SOD2), hemeoxigenase-1 (HO-1), NAD(P)H deydrogenase quinone-1 (NQO1) and catalase genes expression that indicated a compromised redox homeostasis." (PMID 23555779, 2013).
acute liver failure (2 papers, 2024). Rapid deterioration of liver function causing encephalopathy and coagulopathy. "In APAP-induced acute liver failure patients (GSE74000), IKBKG levels decreased, and Nrf2 target genes were also repressed (i.e., HMOX1, PRDX1, TXNRD1, GPX4, GPX1, GCLC, GCLM, and NQO1)." (PMID 38505605, 2024).
acute lung injury (2 papers, 2022 to 2025). A condition of lung damage that is characterized by bilateral pulmonary infiltrates (pulmonary edema) rich in neutrophils, and in the absence of clinical heart failure. "In our previous study, we had shown that SP can improve antioxidant activities and attenuate inflammatory responses through upregulating of Nrf-2/HO-1/NQO1 and downregulating of MAPKs/NF-κB phosphorylation in LPS-stimulated acute lung injury model." (PMID 40248092, 2025). "In our previous study, we demonstrated that anti-oxidative and anti-inflammatory responses of SP were related to the upregulation of Nrf-2/HO-1/NQO1 signaling-mediated suppression of MAPKs/NF-κB phosphorylation in LPS-induced acute lung injury." (PMID 40248092, 2025).
adenoma (2 papers, 2021). A neoplasm arising from the epithelium. "Notably, the mRNA levels for Nqo1 in tumor and peri-tumoral tissues in WT (i.e. Gstp−/−: ApcMin/+: Nrf2+/+: Keap1+/+) mice were highly variable among 12 randomly selected individual animals, suggesting no consistent changes in Nrf2-transcriptional activity during adenoma development." (PMID 34526660, 2021).
allergic asthma (2 papers, 2014 to 2020). A asthma with a basis in a pathological type I hypersensitivity reaction. "In addition, LOL treatment markedly enhanced Nrf-2/HO-1/NQO1 signaling with elevated the activities of anti-oxidant enzymes, such as GSH, CAT, and SOD, and suppressed the levels of ROS, NO, and TBARS in lung tissues of the OVA-challenged allergic asthma model." (PMID 32605045, 2020).
allergic dermatitis (2 papers, 2019 to 2021). "For example, coal tar, used as a treatment for atopic dermatitis, has been reported to increase the expression of NQO1 and Filaggrin via AhR." (PMID 34884772, 2021). "6-Shogaol inhibited ROS production and activated HO-1, NQO1, and Nrf2 in vitro and ameliorated experimental allergic dermatitis-like skin lesions in vivo, and it suppressed Nrf2 expression in the kidney and decreased the levels of blood glucose and HbA1c in diabetic mice." (PMID 31619000, 2019).
anemia (2 papers, 2022 to 2023). A reduction in the number of red blood cells, the amount of hemoglobin, and/or the volume of packed red blood cells. "This compound has been effective in cancers with increased NQO1 expression; however, its sustained use at high concentrations causes anemia in both human and animal models." (PMID 37169843, 2023).
Breast Invasive Carcinoma (2 papers, 2023). "NQO1 mRNA was mostly expressed in Her2, followed by LumB and basal invasive breast carcinoma." (PMID 37583897, 2023).
cataract (2 papers, 2015 to 2022). Partial or complete opacity of the crystalline lens of one or both eyes that decreases visual acuity and eventually results in blindness. "Variant CT heterozygous and TT genotypes of the NQO1 C609T polymorphism were found to be associated with an increased risk of cataracts (CT vs CC, OR=1.61, 95%CI: 1.02-2.52, P=0.038), (CT/TT vs CC, OR=1.56, 95%CI: 1.02-2.4, P=0.040)." (PMID 27844006, 2015). "H2O2-induced cataracts were linked to reduced SOD2 and CAT activities and reinforced NQO-1 activity of the lens." (PMID 35222803, 2022). "The aim of the present study was to investigate the association between NQO1 C609T (Pro189Ser, rs1800566) and CAT promoter C-262T (rs1001179) genetic polymorphisms and the susceptibility to cataracts." (PMID 27844006, 2015). "Genotype distributions of NQO1 and CAT polymorphisms were examined using polymerase chain reactions and a restriction fragment length polymorphism (PCR-RFLP) approach to investigate the possible role of these polymorphisms as risk factors in the development of cataracts." (PMID 27844006, 2015).
cerebrovascular disease (2 papers, 2017 to 2024). "With limited clinical data available, there is a need for additional clinical studies to assess the safety and effectiveness of targeting NQO1 for the treatment of cerebrovascular diseases." (PMID 38167027, 2024). "The future of targeting NQO1 as a potential therapeutic intervention needs a deeper understanding of the complex mechanisms regulating the action of the Nrf2-NQO1 signaling pathway in the development of cerebrovascular diseases." (PMID 38167027, 2024).
cholestasis (2 papers, 2016 to 2022). Impairment of the bile flow caused by obstruction within the liver, or outside the liver in the bile duct system. "Nqo1 is a typical Nrf2 target gene that has been shown to be solely regulated by Nrf2 in BDL-induced cholestasis." (PMID 35696363, 2022). "NQO1 expression was increased as the cholestasis progressed in wild-type mice, which was fully prevented by the absence of Nrf2." (PMID 35696363, 2022). "Particularly, a down-regulation of Car3 and up-regulation of Gadd45a and Nqo1 is indicative of hepatotoxicity, whereas dysregulation of Abcc3 can indicate cholestasis." (PMID 27598887, 2016).
chronic kidney disease (2 papers, 2017 to 2025). Impairment of the renal function secondary to chronic kidney damage persisting for three or more months. "Similar to our results, the expressions of Nrf2 and its direct target Nqo1 were reported to significantly increase in rats with chronic kidney disease to respond favorably to kidney injury and play a critical role in developing vascular calcification." (PMID 38700634, 2025).
chronic myelogenous leukemia (2 papers, 2015 to 2022). "In addition, Xiao and colleagues tested the samples of peripheral blood or bone marrow specimens obtained from patients suffering from chronic myeloid leukemia and showed that the frequency of loss-of-function mutations of the NQO1 gene was higher than that in healthy individuals." (PMID 35056649, 2022). "Studies carried out on chronic myeloid leukemia K562 cells have shown that NQO1 knockdown promoted DNA synthesis and cell growth." (PMID 35056649, 2022).
Cirrhosis (2 papers, 2022 to 2023). A chronic disorder of the liver in which liver tissue becomes scarred and is partially replaced by regenerative nodules and fibrotic tissue resulting in loss of liver function. "We use the bioinformatical analysis to verify that AKR1C3, NQO1, TEK, and TPX2 have good diagnostic performance in patients with cirrhosis." (PMID 36686655, 2022). "The AUCs of expression of AKR1C3, NQO1, TEK, and TPX2 between cirrhosis and HCC were .9.74.77, and .89, proving that the four target genes have predictive value." (PMID 36686655, 2022).
diabetic neuropathy (2 papers, 2018 to 2022). A chronic, pathological complication associated with diabetes mellitus, where nerve damages are incurred due to diabetic microvascular injury involving small blood vessels that supply these nerves, resulting in peripheral and/or autonomic nerve dysfunction. "However, males tend to have an earlier onset of diabetic neuropathy compared to females, suggesting increased dysregulation of microvascular endothelial cells in males compared to females possibly due to reduced NQO1, although this is speculation and requires further investigation." (PMID 36611888, 2022). "This is in contrast to that happens during inflammatory pain or diabetic neuropathy, where SFN increased the expression of NQO1 or re-established its down-regulation in the spinal cord or sciatic nerve, respectively." (PMID 30542282, 2018).
dry eye (2 papers, 2020). "Furthermore, we demonstrated that the topical administration of RS9 induced Nqo1 mRNA expression, but not Gclc mRNA, and ameliorated the vicious symptoms of ocular surface in a rat dry eye model." (PMID 32320433, 2020).
ductal carcinoma in situ (2 papers, 2014 to 2023). "Consistently, we found that there was significantly higher NQO1 expression in lymph node metastases, invasive lobular carcinoma and invasive ductal carcinoma than in ductal carcinoma in situ or nonneoplastic breast tissue." (PMID 37169843, 2023).
endometriosis (2 papers, 2024 to 2025). The growth of functional endometrial tissue in anatomic sites outside the uterine body. "Notable polymorphisms associated with ROS in endometriosis include those for AT-rich interactive domain 1A (ARID1A) and quinone oxidoreductase 1 (NQO1) isoforms." (PMID 40722981, 2025). "Among the three isoforms of quinone oxidoreductase 1 (NQO1), NQO1c was identified as endometriosis-specific (p = 0.0007)." (PMID 40722981, 2025). "One study revealed that endometrial tissue treated with metformin showed regression of lesions in the rat model of endometriosis and the potential mechanism could be the overexpression of NQO1 and markers related to autophagy." (PMID 38922530, 2024).
endometritis (2 papers, 2024 to 2025). An acute or chronic, usually bacterial infectious process affecting the endometrium. "The expression of both the GCLC and NQO1 genes and proteins also decreased in the endometritis group." (PMID 41413615, 2025). "Treatment with chlorogenic acid improved the levels of Nrf2, HO1, and NQO1 and reversed the inflammatory changes to prevent endometritis in Trueperella pyogenes exotoxin-treated mouse endometrial epithelial cells." (PMID 39408650, 2024).
esophagitis (2 papers, 2022 to 2024). An acute or chronic inflammatory disease affecting the esophageal wall. "MTHFR (rs1801133) and NQO1 (rs1800566) were additional risk alleles related to higher susceptibility to pneumonitis and esophagitis overall." (PMID 35912186, 2022). "MTHFR (rs1801133), NQO1 (rs1800566), ZNF217 and POLD1 were risk alleles related to a higher susceptibility to pneumonitis and esophagitis." (PMID 38255239, 2024).
fibroids (2 papers, 2022 to 2025). "Pathway enrichment analysis confirmed significant dysregulation of the NRF2 pathway in this novel leiomyoma subtype (q-value = 3.29 × 10−03), including upregulation of the well-established NRF2 target gene NQO1 (FC = 5.58, q-value = 3.07 × 10−12)." (PMID 36068196, 2022). "Within these 15 pairs, there were four unique genes (NQO1, AC004889.1, TXNL4B, and GGT1), and all four of those genes have not been previously associated with fibroids in the GWAS catalog and were significant only in the African ancestry analysis." (PMID 40050615, 2025). "Leiomyomas of the FH subtype are characterized by activation of nuclear factor, erythroid 2 like 2 (NRF2) target genes, including upregulation of aldo-keto reductase family 1 member B10 (AKR1B10) and NAD(P)H quinone dehydrogenase 1 (NQO1)." (PMID 36068196, 2022).
hepatoblastoma (2 papers, 2020 to 2021). Hepatoblastoma (HB) is a malignant hepatic tumor and is the most common pediatric liver cancer. "In summary, the current results propose a DNA methylation-based classification that explains the genetic and clinical diversity of hepatoblastoma and shed light on the high expression of NQO1 and ODC1, potential druggable targets, in high-risk hepatoblastoma." (PMID 32656360, 2020). "It suggests the possibility that NQO1 expression in hepatoblastoma is highly regulated by the NQO1-ARE." (PMID 32656360, 2020). "Another valuable finding of the current study is the identification of novel therapeutic targets, NQO1 and ODC1, in high-risk hepatoblastoma." (PMID 32656360, 2020). "To assess the synergistic effect of NQO1 inhibition and doxorubicin on NQO1-high hepatoblastoma cell lines, we performed a drug sensitivity assay, which revealed that both NQO1 siRNA and dicoumarol, an NQO1 inhibitor, significantly lowered the EC50 values of doxorubicin." (PMID 32656360, 2020). "Given that quinone-containing anthracyclines play an important role in hepatoblastoma treatment, we hypothesized that high NQO1 expression in hepatoblastoma clusters E1/E2 contributed to chemoresistance and poor outcome." (PMID 32656360, 2020).
Hyperkeratosis (2 papers, 2017 to 2023). Hyperkeratosis is a histopathological term defining a thickened stratum corneum and may be present in many different skin conditions, with many possible overlaps. "Consistent with the Nqo1 and Gclc expression, the hyperkeratosis of the oesophagus and forestomach observed in Keap1−/−::Nrf2Flox/Flox mice was rescued in NEKO mice." (PMID 28233855, 2017). "The increased expression levels of Slpi, Sprr2d, Nqo1, and Epgn in the affected epidermis and cutaneous cysts of a MADISH patient’s skin are reportedly mediated via follicular hyperplasia and hyperkeratosis, as evidenced by a prior study." (PMID 37760426, 2023).
hypoglycaemia (2 papers, 2015 to 2023). "When tested for the effects of MG132, pretreatment with 5μM concentration attenuated the effects of hypoglycemia and restored Nrf2 expression and function, as assessed by an increase in NQO1 immunoreactivity." (PMID 25807533, 2015). "In extension to our previous findings, we first determined the longitudinal effects of hypoglycemia on cell lysate Nrf2 expression and its down-stream target, NQO1 abundantly expressed in BBB endothelial cells." (PMID 25807533, 2015).
influenza (2 papers, 2021 to 2026). An acute viral infection of the respiratory tract, occurring in isolated cases, in epidemics, or in pandemics; it is caused by serologically different strains of viruses (influenzaviruses) designated A, B, and C, has a 3-day incubation period, and usually lasts for 3 to 10 days. "Cyclobakuchiols A–D also upregulated Nqo1 mRNAs in influenza A-infected cells, and cyclobakuchiols A–C, but not cyclobakuchiol D, induced Nrf2 activation in host cells." (PMID 33770117, 2021). "RT-qPCR analyses showed that cyclobakuchiols A–D upregulated Nqo1 mRNAs in influenza A-infected cells, while cyclobakuchiols A–C, but not cyclobakuchiol D, induced Nrf2 activation in host cells." (PMID 33770117, 2021).
liver dysfunction (2 papers, 2021). "NQO1 is highly expressed in human adipose tissue and its expression is reduced during diet-induced weight loss; furthermore its expression correlates directly with adiposity, glycaemia and markers of liver dysfunction." (PMID 34391409, 2021).
mastitis (2 papers, 2024). Inflammation of breast tissue during lactation or postpartum due to an obstructed duct or infection. "When bovine mastitis occurs, decreased KEAP1 and increased Nrf2, HO1, NQO1, and reactive oxygen species (ROS) indicate increased oxidative stress." (PMID 38630770, 2024).
metastatic disease (2 papers, 2019 to 2020). "Nevertheless, assessment of publicly available expression datasets consistently demonstrated significant correlation between decreased NQO1 transcripts and poorly differentiated metastatic tumors, which was in agreement with our experimental data." (PMID 31909204, 2020). "However, it remains to be validated whether NQO1 knockdown potentiates metastatic disease burden in vivo." (PMID 31909204, 2020).
non-alcoholic steatohepatitis (2 papers, 2022 to 2023). "Another report also indicated that Nrf2/NQO-1 signaling pathway played an important role in the therapy of non-alcoholic steatohepatitis using hUC-MSCs." (PMID 37574561, 2023). "For instance, NQO1 is up-regulated while CAT is down-regulated in nonalcoholic steatohepatitis livers." (PMID 35875696, 2022). "An antioxidant enzyme NAD(P)H quinone dehydrogenase 1 (NQO1) is up-regulated while CAT is down-regulated in nonalcoholic steatohepatitis livers." (PMID 35875696, 2022).
pancreatitis (2 papers, 2021 to 2022). Inflammation of the pancreas. "Therefore, the consumption of lycopene-rich foods may prevent the development of alcohol/LPS-associated pancreatitis by activating Nrf2-mediated expression of NQO1 and HO-1, thereby downregulating ROS-mediated IL-6 expression in pancreatic acinar cells." (PMID 35326169, 2022).
polycystic ovary syndrome (2 papers, 2017 to 2025). A disorder that manifests as multiple cysts on the ovaries. "DIC, as an NQO1 inhibitor and an FDA-approved drug, was identified as a potential therapeutic agent targeting core ferroptosis-related genes in polycystic ovary syndrome." (PMID 40007539, 2025).